PPIL1 (peptidylprolyl isomerase like 1)
Description:
Involved in pre-mRNA splicing as component of the spliceosome. PPIases accelerate the folding of proteins. Catalyzes the cis-trans isomerization of proline imidic peptide bonds in oligopeptides. Catalyzes prolyl peptide bond isomerization in CDC40/PRP17. Plays an important role in embryonic brain development; this function is independent of its isomerase activity.
Synonyms: PPIase; CYPL1; CGI-124; PCH14; hCyPX
Tractability: Small molecule: a structure with a bound ligand is known. PROTAC: ubiquitination databases record sites on it; its protein half-life has been measured.
Target class: Isomerase; Enzyme
Gene: Protein-coding gene on chromosome 6 (36,854,825 to 36,875,003, reverse strand). Ensembl gene ENSG00000137168.
Subcellular location: Nucleus
Subcellular location (Human Protein Atlas): Nucleoli
Pathways (Reactome):
Disease: Dengue Virus-Host Interactions
Metabolism of RNA: mRNA Splicing - Major Pathway
Gene Ontology:
Molecular function: disordered domain specific binding; peptidyl-prolyl cis-trans isomerase activity; protein binding
Biological process: embryonic brain development; mRNA splicing, via spliceosome; protein peptidyl-prolyl isomerization; protein folding
Cellular component: catalytic step 2 spliceosome; nucleolus; nucleus; post-mRNA release spliceosomal complex; post-spliceosomal complex; spliceosomal complex; U2-type catalytic step 1 spliceosome; U2-type catalytic step 2 spliceosome; nucleoplasm
Genetic constraint (gnomAD): Loss-of-function variants: 14 observed, 20.4 expected, observed/expected ratio (o/e) 0.69, 90% interval 0.45 to 1.07. The upper end of that interval is the gene's LOEUF score, 1.07, which puts it in group 4 of 6, group 1 being the genes least tolerant of losing a copy. Missense variants: 192 observed, 228.81 expected, observed/expected ratio (o/e) 0.84, 90% interval 0.75 to 0.95. Synonymous variants: 72 observed, 77.57 expected, observed/expected ratio (o/e) 0.93, 90% interval 0.77 to 1.13.
Homologues: Orthologues: chimpanzee PPIL1 (100% identical), dog PPIL1 (100% identical), macaque PPIL1 (100% identical), pig PPIL1 (100% identical), rabbit PPIL1 (100% identical), guinea pig PPIL1 (99% identical), rat Ppil1 (99% identical), mouse Ppil1 (98% identical), zebrafish ppil1 (85% identical), tropical clawed frog ppil1 (83% identical), Drosophila melanogaster Cypl (73% identical), Caenorhabditis elegans cyn-12 (66% identical). Paralogues in human: PPWD1 (51% identical), PPIL2 (49% identical), CWC27 (48% identical), PPIC (48% identical), PPIB (46% identical), PPID (46% identical), PPIA (45% identical), PPIF (45% identical), NKTR (43% identical), PPIE (43% identical), PPIL3 (43% identical), PPIAL4C (42% identical), and 10 more.
Diseases named in the same sentence as PPIL1 in open-access papers:
PPIL1 is named in the same sentence as 12 diseases in open-access papers, as found by Europe PMC text mining. Sharing a sentence is not in itself a finding about the gene and the disease. The quoted sentences say what the papers report.
colon cancer (4 papers, 2010 to 2021). "PPIL1 has also been reported to be upregulated in colon cancer tissues, and capable of promoting the growth of colon cancer cells through SNW1/SKIP and/or stathmin." (PMID 26020957, 2015). "PPIL1 is up-regulated in human colon cancer cells and an siRNA-mediated knockdown of PPIL1 resulted in a reduced number of viable cells." (PMID 20368803, 2010). "Furthermore, the remaining SF PPIL1, which has not been directly reported in the literature to be associated with cancer, is a member of the peptidyl-prolyl isomerase procyclin family and is frequently overexpressed in colon cancer cells." (PMID 35126467, 2021).
microcephaly (4 papers, 2023 to 2025). A congenital or acquired developmental disorder in which the circumference of the head is smaller than normal for the person's age and sex. "Similarly, EFTUD2 mutations result in mandibulofacial dysostosis with microcephaly, and mutations in PPIL1, PRP17, and PRPF19 are linked to neurodegenerative pontocerebellar hypoplasia." (PMID 40608414, 2025). "Recently, bi-allelic variants in PPIL1 and PRP17 have been demonstrated to cause a phenotypically very similar disorder of microcephaly with pontocerebellar hypoplasia, with little impact on other body systems." (PMID 40857589, 2025). "Compared to the individuals described here, the PPIL1/PRP17-associated cohort had milder microcephaly, and structural anomalies were not as severe on brain imaging." (PMID 40857589, 2025).
breast carcinoma (1 paper, 2021). "Correlation analysis with Glo1 expression gave the following: pan cancer—PPIL1, r = 0.59 and CDC5L, r = 0.58 (p < 1 × 10−6) and TRADD, r = −0.17 (p = 5 × 10−4); and for breast cancer—PPIL1, r = 0.55; CDC5L, r = 0.26 and TRADD, r = −0.20 (p < 1 × 10−6)." (PMID 34790575, 2021).
cancer (3 papers, 2021 to 2022). A tumor composed of atypical neoplastic, often pleomorphic cells that invade other tissues. "The authors showed, using the Cancer Cell Line Encyclopedia (CCLE) that GLO1 mRNA expression positively correlated with the expression of spliceosome proteins (PPIL1 and CDC5L), suggesting increased GLO1 expression protects spliceosome proteins in tumour cells." (PMID 35409048, 2022).
tumor (3 papers, 2021 to 2024). "An activating product of C3b forms a complex with PPIL1 (Peptidylprolyl Isomerase Like 1), which induces NLRP3 inflammasome formation, as evidenced by caspase-1-dependent IL-1β activation, to promote tumor metastasis." (PMID 38894892, 2024).
infection (1 paper, 2017). The state of being infected such as from the introduction of a foreign agent such as serum, vaccine, antigenic substance or organism. "Out of these LENG1 and PPIL1 were also down regulated in H37Rv infected macrophages at 48 hours post-infection." (PMID 28257432, 2017).
neurodegenerative disease (1 paper, 2024). A disorder of the central nervous system characterized by gradual and progressive loss of neural tissue and neurologic function. "PPIL1 plays a crucial role as an enzyme-substrate pair within the spliceosome, exerting its function in the facilitation of RNA splicing and ensuring the survival of neurons, and its mutations may cause neurodegenerative disease." (PMID 39045051, 2024).
PPIL1 also shares sentences with these, for which no sentence is quoted: developmental delay (1 paper); endometrial cancer (1); Hydrocephalus (1); mandibulofacial dysostosis (1); psychiatric disorder (1).